MYEOV (myeloma overexpressed)
Diseases named in the same sentence as MYEOV in open-access papers (continued):
Sharing a sentence is not in itself a finding about the gene and the disease.
tumor (16 papers, 2015 to 2025). "Through the comprehensive analysis of multiple databases, we constructed a molecular network centered on MYEOV and found specific links between molecules in this network and tumor-associated immune cells." (PMID 36358856, 2022). "The immune infiltration analysis of genes in the MYEOV-related molecular network in this present study showed that these genes might promote an immunosuppressive phenotype through various tumor-associated immune cells under the regulation of MYEOV." (PMID 36358856, 2022). "Further molecular analysis revealed that MYEOV acts as a tumor promoter by associating with MYC to facilitate oncogenic miR-17/93-5p expression in PDAC progression and may provide a potential therapeutic strategy for PDAC patients." (PMID 34930894, 2021). "Given the current insufficient understanding of the role of MYEOV in tumor drug resistance and immune status alterations, it is necessary to conduct more preclinical and clinical trial studies to obtain more precise information." (PMID 40535130, 2025). "In this review, we have delved into the multifaceted roles of MYEOV in the tumor microenvironment and highlighted its significant functions in tumorigenesis." (PMID 40535130, 2025). "The role of MYEOV in various tumors is not limited to its direct effects as an oncogene; it also includes its complex role in tumor cell signaling pathways and its ability to participate in miRNA regulatory networks as a competing endogenous RNA (ceRNA)." (PMID 40535130, 2025). "This article aims to provide a comprehensive review of the role of MYEOV, its involvement in signaling pathways in tumor cells, and the latest advancements in MYEOV-targeted therapies." (PMID 40535130, 2025). "Note repressed expression of RASGRF1 and DMBT1 was associated with increased tumor size, and high expression of FOSL1, FAM83A and MYEOV was associated with poor survival." (PMID 38245882, 2024). "More recently a paper reported MYEOV protein expression in PDAC, where they have shown both via immunohistochemistry and western blots that tumour cells exhibit MYEOV protein expression." (PMID 39139450, 2024). "Further research is needed to understand how the MYEOV protein as well as the MYEOV transcript itself contribute to tumor progression." (PMID 36698109, 2023). "In vivo, MYEOV knockdown reduced tumor invasion and metastasis, reduced expression signatures characteristic of the EMT, and reduced TGF-B signaling; constitutive activation of TGF-B signaling rescued these phenotypes." (PMID 35451603, 2022). "In two cell lines, MYEOV knockdown reduced cell migration, invasion, and proliferation in vitro and reduced tumor weight and liver metastasis formation in vivo." (PMID 35451603, 2022). "Having demonstrated that MYEOV can promote tumor progression, we further investigated MYEOV-mediated changes in the global transcriptome in MYEOV-depleted PDAC cells (PANC-1 and AsPC-1) by mRNA-Seq." (PMID 34930894, 2021). "Depletion of MYEOV significantly affected tumor formation induced by PDAC cells in a xenograft mouse model." (PMID 34930894, 2021). "By conducting a comprehensive analysis of the expression patterns of MYEOV and their correlations with patient prognosis, tumor-infiltrating immune cells, and the expression of immune checkpoint genes, we have further anticipated the potential application prospects of MYEOV in tumor immunotherapy." (PMID 40535130, 2025). "In ESC cell lines, MYEOV is co-amplified with CCND1 in the primary tumor." (PMID 40535130, 2025). "The knockout of the MYEOV gene can inhibit cell proliferation in vitro and tumor growth in vivo." (PMID 40535130, 2025). "MYEOV is a 313-amino acid protein that emerged in the human lineage, first identified in a screen for the ability of DNA from gastric carcinoma to induce tumor formation." (PMID 35451603, 2022). "Meanwhile, silencing MYEOV transcript in H1975 inhibited subcutaneous tumor invasiveness." (PMID 30181549, 2019).
tumor (continued). "Tumor-bearing mice that exhibit high MYEOV expression revealed shorter survival time." (PMID 30181549, 2019). "The absence of MYEOV disrupts the transcriptional mechanism of miRNAs, leading to the abnormal expression of miRNAs in tumor cells." (PMID 40535130, 2025). "Furthermore, the mRNA expression levels of FAM83A, LY6D, MET, MUC16, MYEOV, and WNT7A were elevated in PAAD tissues, while the protein expression patterns of LY6D, MET, MUC16, and WNT7A were higher in tumor sample." (PMID 38169540, 2024). "The acidosis-related signature is composed of seven key genes (ARNTL2, DKK1, CEP55, CTSV, MYEOV, DSG2, and GBP2), all of which have elevated expression levels in PC tumor tissues compared with normal tissues and are all related to adverse clinical outcomes in patients with PC." (PMID 34993253, 2021). "Further experiments demonstrated that the MYEOV ceRNA sequestered miR-30c-2-3p from binding its targets TGFBR2 and USP15 mRNAs, which in turn leading to constitutive activation of TGF-β signaling and tumor progression in NSCLC." (PMID 30181549, 2019). "Consistent with the in vitro findings, significant decreases in the tumor volume and growth rates were observed in mice injected with MYEOV-knockdown PANC-1 cells compared with those in the negative control group, whereas mice injected with MYEOV-overexpressing cells showed the opposite effect." (PMID 34930894, 2021). "Independent of its protein-coding capacity, MYEOV transcript exerts its pro-metastatic function via abrogating the suppression of TGFBR2 and Ubiquitin specific protease 15 (USP15) expression by miR-30c-2-3p, leading to constitutive activation of TGF-β signaling and tumor progression in NSCLC." (PMID 30181549, 2019).
MYEOV also shares sentences with these, for which no sentence is quoted: multiple myeloma (5 papers); colon cancer (3); head and neck squamous cell carcinoma (2); neuroblastoma (2); pancreatic adenocarcinoma (2); benign prostatic hyperplasia (1); Esophageal Neoplasms (1); gastric adenocarcinoma (1); kidney cancer (1); metastatic tumor (1); oral squamous cell carcinoma (1); ovarian serous cystadenocarcinoma (1); prostate carcinoma (1); stomach cancers (1).